HMGB1 (high mobility group box 1)
Diseases named in the same sentence as HMGB1 in open-access papers (continued):
Sharing a sentence is not in itself a finding about the gene and the disease.
infection (continued). "Furthermore, by overexpressing HMGB1, we showed that this regulation of HMGB1 levels during infection is critical for optimal HAdV-C5 replication." (PMID 40919947, 2025). "However, under stress conditions such as infection, injury, or inflammation, HMGB1 can be released into the extracellular space, where it acts as DAMP." (PMID 40688353, 2025). "Extracellular HMGB1 functions as an alarmin or damage-associated molecular pattern (DAMP) and mediates immune cell migration to the site of tissue damage to protect against possible infection." (PMID 40308590, 2025). "Following the observation of cell specific HMGB1 translocation after HAdV-D37 infection, we tested several different HAdVs to explore whether HMGB1 secretion by corneal epithelial cells was also virus-specific." (PMID 40367285, 2025). "We believed that there might be an initial factor that increases inflammation by increasing the gene expression level of proinflammatory cytokines by activating the HMGB1/TLR4/RAGE/NF‐κB pathway due to infection." (PMID 39046369, 2024). "HMGB-1 mRNA expression increased in all groups after infection with S. typhi (day 4)." (PMID 39416736, 2024). "HMGB1 is an important factor mediating infection, tissue injury, and inflammation." (PMID 39445002, 2024). "Recently, HMGB1 was found to be a potent pro-inflammatory cytokine during infection." (PMID 38800022, 2024). "Multiple studies have also outlined potential therapeutic roles of HMGB1 in infection and injury." (PMID 39682695, 2024). "Animal studies using infected mice have reported high HMGB-1 levels after infection." (PMID 39416736, 2024). "HMGB-1 levels in the context of infection have been previously evaluated." (PMID 39416736, 2024). "Finally, we demonstrate that protein VII represses the immune response to infection by dampening transcription of interferon beta (IFNβ) in an HMGB1-dependent manner." (PMID 37703278, 2023). "HMGB1 intensifies the sterile inflammation correlated with infection and thrombosis." (PMID 36675299, 2023). "Interestingly, we also noted by western blot that it was mostly pVII that was found in the insoluble fraction during infection when HMGB1 was also insoluble, suggesting that in human cells, HMGB1 likely does interact with pVII." (PMID 37703278, 2023). "Given the direct interaction between protein VII and HMGB1, we next hypothesized that protein VII binds specifically to the A-box of HMGB1 within the nucleus during infection." (PMID 37703278, 2023). "Thus, human or mouse HMGB1 protein not only functions as a nuclear factor but also functions as a vital cytokine mediating responses to infection, injury, and inflammation." (PMID 38020710, 2023). "Meanwhile, HMGB1 translocation was observed in the early time point of infection (24 h.p.i)." (PMID 35058496, 2022). "During an infection, LPS triggers hepatocytes to release HMGB1 into the circulation." (PMID 36189354, 2022). "When the infection was prolonged to 24 h, the interaction between HMGB1 and RPS3 still existed." (PMID 35632744, 2022). "HMGB-1 is also released by parasites during the infection process, and it has been documented that it may play an important function in the treatment response." (PMID 36139753, 2022). "During infection or injury, HMGB1 also functions outside the nucleus." (PMID 36611692, 2022). "Monocytes are inflammatory cells that release HMGB1 in response to injury and infection." (PMID 36497194, 2022). "Thus, in spite of the significant correlation of infections and elevated HMGB1 levels, this sample size is too small for strong conclusions." (PMID 34671818, 2022). "It is possible that blocking the release of HMGB1 may be a viable broad-spectrum anti-disease strategy as HMGB1 protein is released during infection by most pathogens." (PMID 36139393, 2022). "HMGB1 also functions as an acute-phase cytokine during infection." (PMID 36562037, 2022).
infection (continued). "HMGB1 activates TLRs receptors and is extensively involved in the infection process of pathogens." (PMID 36139393, 2022). "Similar results have been reported during infection with influenza A H1N1 virus: HMGB1 is released by necrotic cells, inducing an exacerbated production of cytokines and inflammatory mediators such as IL-1ß, TNF-α, IL-6, and IL-23, and promoting alteration of the blood–brain barrier (BBB)." (PMID 36016387, 2022). "Thus, excessive HMGB1 release contributes to the pathogenesis of lethal infections by posing divergent adverse effects such as immune tolerance, immune paralysis and immunosuppression." (PMID 34571869, 2021). "Western blot analyses revealed that lenti-shHMGB1 infection remarkably decreased HMGB1 expression which resulted in significant upregulation of mRNA level of the macrophage-like differentiation markers (CD14, CD11b, and CSF1R) as compared with the lenti-ctrl infection." (PMID 33128580, 2021). "In our experiments, the infection with E. coli O55 downregulated HMGB1 mRNA expression." (PMID 34439812, 2021). "Thus, the infection/inflammation-modified expression of HMGB1, RAGE, and TLR4 showed a therapeutic potential of these biomolecules." (PMID 34439812, 2021). "Therefore, using both chemical inhibitor and siRNA-specific knockdown, we have shown that HMGB1 plays an important role in BoHV-1 productive infection in MDBK cells." (PMID 34008469, 2021). "HMGB1 released to the extracellular space is an attractive candidate for therapy, because of its function as a late mediator of inflammation, with levels highest levels attained at 2–3 days after infection." (PMID 34684184, 2021). "Moreover, the infection with E. coli O55 upregulated the release of HMGB1 that belongs to the TLR2 ligands, and thus can also stimulate this signaling pathway." (PMID 34439812, 2021). "One of the possible sources of HMGB1 in the amniotic fluid may be the constitutive secretion by the amnion, which can be emphasized by its infection or injury." (PMID 34439812, 2021). "Extracellular HMGB1 and ATP significantly increased from 48 h post-infection." (PMID 33665363, 2021). "HMGB1 is a nuclear protein released extracellularly during proinflammatory lytic cell death or secreted by activated macrophages, NK cells, and additional cell types during infection or sterile injury." (PMID 33975537, 2021). "The cytokine-like function of HMGB1 upon inflammatory stimuli after infection or injury relies on the interaction of its reduced form with CXCL12, which promotes CXCR4-dependent recruitment of inflammatory cells to injured tissues and exacerbates the immune response in pathological conditions." (PMID 33324614, 2020). "It would be beneficial to assess whether the expression of HMGB1 changes at other time points of infection, especially at the onset and toward the end of infection." (PMID 32796569, 2020). "Infection, injury, and necrosis leads to release of high mobility group box 1 (HMGB1) protein." (PMID 33266387, 2020). "Likewise, high level of HMGB1 was released in the medium, especially at later time point (48 h), after infection of cells with the virus." (PMID 31209267, 2020). "In our study, we assessed the HMGB1 gene expression in the early phase of infection, which would further support the hypothesis of genetic predisposition towards CDI." (PMID 32796569, 2020). "Nuclear HMGB1 is an architectural chromatin-binding factor responsible for maintaining genome integrity, whereas extracellular HMGB1 is a mediator of inflammation and immune dysfunction in response to various stresses, including starvation, oxidative damage, hypoxia, and pathogen infection." (PMID 32442210, 2020).
infection (continued). "Similarly, the mouse cell lines NIH-3T3 and 3T6-Swiss secreted HMGB1 upon infection with Herpes simplex virus strain HSV1716, an oncolytic herpes virus." (PMID 33424893, 2020). "In addition, leukocytes have been identified as professional cells for HMGB1 release upon injury and infection." (PMID 32670275, 2020). "Moreover, HMGB1 mRNA levels in these cells have been demonstrated to increase, which means that the pulp infection also stimulates the synthesis of this molecule." (PMID 32760399, 2020). "The infection mediated a dose-dependent ATP and HMGB1 release from Sting wild-type cells." (PMID 33213060, 2020). "Intracellular HMGB1 is involved in autophagy and vesicle formation, and extracellular HMGB1 is considered to be an important mediator of inflammation after cell damage or infection." (PMID 32566664, 2020). "Furthermore, reinfection of RAGE deficient mice with PVM 42 days after initial infection resulted in increased AHR and goblet cell hyperplasia compared to WT mice, and these endpoints were reduced with the antibody neutralization of HMGB1." (PMID 32397226, 2020). "Secondly, we measured the HMGB1 gene expression only at a single time point of infection." (PMID 32796569, 2020). "While influenza virus does not express TLR4 pathogen-associated molecular patterns (PAMPs), infection elicits increased levels of a host-derived damage-associated molecular pattern (DAMP), high-mobility-group box 1 (HMGB1), shown previously to be a TLR4 agonist." (PMID 31064834, 2019). "In contrast, HMGB1 expression was unaffected by ST infection or commensal/probiotic administration." (PMID 31847111, 2019). "Given the marked necrotic fields in the liver sections from Gal-3 KO mice and the ability of MCMV to induce necroptosis, we examined markers of necroptotic death, HMGB1 in liver tissue homogenates and membrane expression of calreticulin on hepatocytes, 36 h after infection." (PMID 30800112, 2019). "Given the CBX’s capacity in blocking Cx43 GJ and hemichannel activities, we reasoned that macrophage Cx43 hemichannels might also be involved in the regulation of HMGB1, a key mediator of injury- and infection-elicited inflammatory diseases." (PMID 29317708, 2018). "Therefore, HMGB1 has multiple functions in infection, tissue injury, inflammation, apoptosis, and immune response." (PMID 29795561, 2018). "The over-secretion of HMGB1 extracellularly could lead to severe infections or tissue damage, thereby triggering inflammatory disease." (PMID 29702580, 2018). "HMGB1 initiates and perpetuates immune responses during infections." (PMID 30157804, 2018). "However, HMGB1 has also been suggested to mediate neuro-inflammatory priming in the aged brain and HMGB1 antagonism prevented prolonged infection-induced neuro-inflammatory and sickness responses in aged rats treated with live E. coli." (PMID 29755322, 2018). "PGLYRP1 could form homodimers for its antimicrobial activity and could be induced in response to the infection; HMGB1 and actin are the cellular proteins and could be released from the cells in inflammatory conditions." (PMID 29619033, 2018). "Many reports document abundant HMGB1 release following infection with oncolytic viruses (OVs)." (PMID 29543735, 2018). "If our hypothesis that HMGB1 is secreted due to infection were correct, we would then expect to identify high levels of the protein in the sera of infected mice." (PMID 30258438, 2018). "The increase in HMGB1 levels correlated with the decrease in HLA-DR expression (r = −0.46, p = 0.04), and peak HMGB1 concentrations were significantly higher in the five patients who went on to develop a postoperative infection (p = 0.04)." (PMID 29675023, 2018). "Therefore, we included both influenza type A and B viruses in our study and measured serum HMGB1 levels systematically before and after infection." (PMID 29535197, 2018).
infection (continued). "Overall, our data indicate that the kinetics of induction of serum HMGB1 parallels the length of time of the replication cycle and relative levels correlate with severity of infection by these viruses in cotton rats as defined by the extent of lung cytokine expression and pathology (30, –, 33)." (PMID 29535197, 2018). "Comparison of serum HMGB1 responses in cotton rats upon infection by other respiratory viruses." (PMID 29535197, 2018). "Serum HMGB1 induction upon infection by various strains of influenza A virus in cotton rats." (PMID 29535197, 2018). "Furthermore, HMGB1 levels were related to the occurrence of postoperative infections in CRS-HIPEC patients." (PMID 29675023, 2018). "Interestingly, blocking HMGB1 during the primary PVM infection also served to increase IFN–α and IFN-λ production and reduced viral load in RAGE deficient mice." (PMID 28099113, 2017). "As shown in the mouse infection model, strong inflammation responses are arising at the inoculation foci, and it can be presumed that the proinflammatory reaction may be related to the high expression and secretion of HMGB1 at the early stage of infection." (PMID 28484433, 2017). "HMGB-1 also has antibacterial activity; thus elevated expression of this protein may represent a mechanism used by the immune system to combat infection in addition to being a marker of cellular damage." (PMID 28286376, 2017). "Dot blotting showed the release of HMGB1 from cells treated with EnAd and Ad11p started at 3 days post infection (POI), reaching a maximum at day 3.5–4, whereas Ad5-treated cells gave only a weak signal even at day 4, when death of most cells was verified by MTS and xCELLigence." (PMID 28345021, 2017). "HMGB1 played an important role in driving ASM remodelling during the primary PVM infection." (PMID 28099113, 2017). "Simultaneously, Ana1 cells began to secret HMGB1 to the supernatant soon after infection." (PMID 28484433, 2017). "HMGB1 is an essential cytokine that mediates the response to infection, injury and inflammation." (PMID 27603014, 2016). "Generally, HMGB-1 is regarded as an endogenous “alarmins,” which serves as danger signals and cytokines to promote the activation of the innate immunity in response to trauma, ischemia/reperfusion, or infection." (PMID 26115623, 2016). "The HMGB1 expression is induced in mice on days 3-7 post infection." (PMID 27634894, 2016). "Numerous activated and apoptotic macrophages showed HMGB1 immunostaining during early infection." (PMID 26201072, 2015). "This study also reportedHMGB1 released in lungs during infection with Mtb in guinea pigs, and concluded that HMGB1 may acts as a signal of cellular injury that enhances immune response." (PMID 26201072, 2015). "In order to study the contribution of HMGB1 to immunopathology during early M. tuberculosis infection (first month), infected mice were treated with HMGB1 blocking antibodies during the first three weeks of infection." (PMID 26201072, 2015). "Regardless of the origin, the actively secreted or passively released HMGB1 can similarly alert, recruit, and activate immune cells, triggering infection- and injury-elicited systemic inflammatory responses that are often indistinguishable in experimental or clinical settings." (PMID 26257917, 2015). "In contrast, during the early phase of the infection the most common HMGB1 immunostained cells were the bronchial epithelium with a constant 70–80% of positive cells determined by automated morphometry, while at late disease occasional epithelial cells showed scarce immunoreactivity." (PMID 26201072, 2015). "In order to study the course of the infection during late TB with similar high concentrations of HMGB than those found during early infection, a high concentration of recombinant HMGB1 was administered after 60 days of infection by intratracheal route during one month." (PMID 26201072, 2015).
infection (continued). "Thus, infection and injury converge in a common process, i.e., inflammation, which is orchestrated by HMGB1 and other proinflammatory mediators (e.g., mitochondrial DNA and CIRP) released by activated immune cells and damaged tissues." (PMID 26257917, 2015). "The capacity to facilitate endocytic HMGB1 uptake by professional phagocytes may provide the basis for the treatment of both infection- and injury-elicited inflammatory diseases." (PMID 26257917, 2015). "In particular, oxidative stress-associated human aging and many diseases have been increasingly recognized as central regulators of HMGB1 biology in infection, sterile inflammation, and cell death types such as necrosis, apoptosis, autophagic cell death, pyroptosis, and NETosis." (PMID 25904867, 2015). "HMGB1, which is secreted from immunologically activated innate immune cells and is released from pathologically damaged cells, functions as a critically important mediator in lethal infection and injury." (PMID 26257917, 2015). "Based on our computed results, we concluded that a Healing Process occurs when the level of pathogens, level of phagocytic cells (neutrophils and monocytes), and level of inflammatory cytokines (TNF-α, HMGB-1, and IL-10) oscillate below threshold during infection." (PMID 26446682, 2015). "The maximal concentration of HMGB1 in BALF was at day one of infection." (PMID 26201072, 2015). "Interestingly, however, the attenuation of RAGE expression was seen only in the early phase of infection (day 3) in anti-HMGB1 mAb-treated mice, although HMGB1 level was suppressed significantly in both serum and BALF at all time points." (PMID 26067826, 2015). "Not only can HMGB1 bind to double-stranded DNA and interact with other DNA-binding proteins to facilitate chromatin binding, but also function as a nuclear factor to enhance transcription in response to infection, inflammation, and tissue injury." (PMID 24923305, 2014). "However, the HMGB1 mRNA was decreased to undetectable levels in both groups on day 7 post-infection." (PMID 24651485, 2014). "In this study, we aim to clarify whether HMGB1 is correlated with intestinal mucosal barrier injury and infection of SAP; and the relationships between their serum HMGB1 levels and various clinical factors for SAP were also analyzed." (PMID 25926862, 2014). "Importantly, expression and acetylation of HMGB1 were also significantly down-regulated in fip200 KO mice following PAO1 infection." (PMID 24923305, 2014). "Furthermore, relationship between their serum HMGB1 levels and intestinal barrier injury, infection and other clinical factors were analyzed." (PMID 25926862, 2014). "Collectively, these findings elucidate that FIP200 may regulate expression and translocation of HMGB1 during PAO1 infection, which may indicate novel therapeutic targets to control pulmonary infection." (PMID 24923305, 2014). "The results demonstrated infection triggered release of HMGB1." (PMID 24524027, 2014). "Furthermore, correlation between serum HMGB1 levels and blood biochemical parameters, intestinal mucosa barrier, and infections in patients with SAP were also analyzed." (PMID 25926862, 2014). "Our study demonstrates that HMGB1 produced by fetal membranes causes autocrine activation of p38MAPK-mediated senescence-associated inflammation independent of infection." (PMID 25469638, 2014). "Reg3γ, a protein with antibacterial and regenerative functions released by epithelial cells in response to infection and damage, and the alarmin HMGB1 were also detected in higher amounts in the BALF of C57BL/6J than Elane−/− mice, consistent with the increased tissue damage." (PMID 25166912, 2014). "Since HMGB1 is elevated during infection, strategies to reduce HMGB1 activity using antibodies may be therapeutically effective." (PMID 25187820, 2014). "HMGB1 has multiple functions in infection, organ dysfunction, inflammation and immune responses." (PMID 25284457, 2014).